MIR134 (microRNA 134)
Synonyms: hsa-mir-134; MIRN134; mir-134
Gene: MicroRNA gene on chromosome 14 (101,054,687 to 101,054,759, forward strand). Ensembl gene ENSG00000207993.
Gene Ontology:
Biological process: miRNA-mediated post-transcriptional gene silencing
Cellular component: RISC complex
Homologues: Orthologues: chimpanzee ptr-mir-134 (100% identical), guinea pig MIR134 (97% identical), mouse Mir134 (95% identical).